PPARG (peroxisome proliferator activated receptor gamma)
Diseases named in the same sentence as PPARG in open-access papers (continued):
Sharing a sentence is not in itself a finding about the gene and the disease.
renal fibrosis (39 papers, 2011 to 2025). A final common manifestation of a wide variety of chronic kidney diseases characterized by glomerulosclerosis and tubulointerstitial fibrosis. "For instance, the development of glomerulosclerosis and renal fibrosis associated with TGF-β activation could be significantly repressed by the treatment with one PPARγ agonist pioglitazone." (PMID 35380292, 2022). "While TGF-β/Smad and Wnt/β-catenin represent the most extensively characterized pathways in renal fibrosis, recent studies highlight the roles of mechanistic target of rapamycin (mTOR) and peroxisome proliferator-activated receptor gamma (PPARγ)." (PMID 40141260, 2025). "To investigate the role of PPAR activation in obstruction-induced renal fibrosis, we administered the PPARγ agonist pioglitazone to UUO mice." (PMID 40432888, 2025). "Another member of the PPARs family, PPARγ, has been reported to repress renal fibrosis by alleviating extracellular matrix (ECM) accumulation and the course of DN." (PMID 40486272, 2025). "Another PPARγ agonist, pioglitazone, similarly prevents renal fibrosis by repressing the TGF-β signaling pathway." (PMID 36902313, 2023). "Mechanistically, Nephropathy 1st regulated fatty acid metabolism via activating PPARγ signaling pathways, the inactivation of which contributed to renal fibrosis." (PMID 36339588, 2022). "In this study, PPARγ was also found to be downregulated in renal fibrosis models, while Nephropathy 1st treatment activated PPARγ signaling." (PMID 36339588, 2022). "PPARγ agonists appear to be useful in reversing this early stage of the renal fibrosis (epithelial-mesenchymal transition, EMT) in the condition of the high glucose and to restore the function of SGLT-proteins mediated glucose uptake." (PMID 32158560, 2020). "Oral administration of PPARγ agonist pioglitazone significantly reduces TGF-β1-driven renal fibrosis, via the attenuation of EGR-1, STAT3 and AP-1." (PMID 31277592, 2019). "In the present study, we examined the effect of PPARγ activation on the transcriptional regulation of renal fibrosis in TGF-β1 transgenic mice." (PMID 31277592, 2019). "Further studies revealed that improved renal fibrosis and function in diabetic rats were associated with inactivation of ERK1/2 and PPARγ signaling pathways." (PMID 27145370, 2016). "PPARγ agonists possess antifibrotic potential that results in attenuation of renal fibrosis after chronic injury." (PMID 22174924, 2011). "However, the inhibition of PPARγ abrogated the beneficial effects of Nephropathy 1st and promoted renal fibrosis in vivo and in vitro." (PMID 36339588, 2022). "PPARγ agonists were also found to inhibit renal interstitial macrophage infiltration, downregulate the expression of downstream target genes, and upregulate bone morphogenetic protein-7 expression, eventually blocking renal fibrosis." (PMID 35308207, 2022). "Another PPARγ agonists, pioglitazone, reduced renal fibrosis and its progression." (PMID 35308207, 2022). "The results suggest that Nephropathy 1st may improve renal fibrosis by altering the production of certain types of metabolites and the related PPARγ signaling pathways." (PMID 36339588, 2022). "In conclusion, Nephropathy 1st suppressed renal fibrosis via activating PPARγ signaling." (PMID 36339588, 2022). "In conclusion, Nephropathy 1st alleviates renal fibrosis development in a PPARγ-dependent manner." (PMID 36339588, 2022). "Our results might help to clarify the beneficial role of PPARγ in preventing or reversing TGFβ1-driven renal fibrosis." (PMID 31277592, 2019). "Our present study shows an additional potential interplay of STAT3 and PPARγ in renal fibrosis, as STAT3 was activated in kidneys of untreated TGF-β1 transgenic mice, but STAT3 activation was absent in kidneys of TGF-β1 transgenic mice chronically treated with pioglitazone." (PMID 31277592, 2019).
renal fibrosis (continued). "It has been proposed that peroxisome proliferator-activated receptor-γ (PPARγ) agonists might reduce renal fibrosis, however, several studies had contradictory results." (PMID 31277592, 2019). "Additionally, PPARγ’s therapeutic benefit has significant overlap with several of the previously discussed targets in this section, including BMPR2 and TGF-β signaling and the RAS system as Ang II inhibition increased PPARγ expression in murine models of renal fibrosis." (PMID 36986517, 2023). "Thus, we hypothesized that curcumin may inhibit renal fibrosis as assessed by EMT through PPARγ pathways in the TGF-β signaling." (PMID 23544048, 2013). "Peroxisome proliferator-activated receptor gamma (PPARγ) regulates phosphatase and tensin homolog (PTEN), consequently negatively modulating the PI3K/AKT pathway and attenuating renal fibrosis." (PMID 41415577, 2025). "For instance, PPARγ agonist pioglitazone was recently shown to suppress TGF-β (tumor growth factor beta)-induced glomerulosclerosis and renal fibrosis." (PMID 35380292, 2022). "Troglitazone, another PPARγ agonists, also attenuated renal interstitial fibrosis and inflammation in the unilateral ureteral obstruction's animal (UUO), a classic renal fibrosis model." (PMID 23544048, 2013). "Furthermore, curcumin ameliorates renal fibrosis by inhibiting local fibroblast proliferation and ECM deposition, upregulating the expression of peroxisome proliferator-activated receptor gamma (PPAR-γ), and downregulating the expression of p-Smad2/3." (PMID 40308781, 2025). "Pharmacologic activation of PPARγ inhibited dermal fibrogenesis by suppressing the early growth response protein 1, a mediator of non-Smad TGF-β1 signaling, and maintained normal epithelial phenotype, prevented renal fibrosis and oxidative stress in mice." (PMID 31557909, 2019). "Here, we aimed to study whether the chronic administration of PPARγ agonist pioglitazone could influence renal EGR-1, STAT3 and AP-1 expression, and ameliorate renal fibrosis in TGF-β1 overexpressing mice." (PMID 31277592, 2019). "Moreover, the possible interaction of TGF-β1, PPARγ, and transcription factors in renal fibrosis have not been investigated." (PMID 31277592, 2019). "Interestingly, despite a beneficial effect of the (otherwise liver-toxic) PPARγ agonist troglitazone was reported in the unilateral ureter obstruction (UUO) model of renal fibrosis, others could not confirm these results using pioglitazone." (PMID 31277592, 2019). "Similar to their effect on renal fibrosis, irbesartan, but not losartan, treatment significantly reduced fibrosis in the heart, whereas the reduction of fibrosis in the heart by irbesartan was also attenuated by treatment with GW9662, a PPARγ antagonist, or anti‐HGF neutralizing antibody." (PMID 23608606, 2013).
ovarian carcinoma (38 papers, 2004 to 2025). A malignant neoplasm originating from the surface ovarian epithelium. "A body of evidence suggests that there is a significant association between the role of apelin and peroxisome proliferator-activated receptor gamma (PPAR) in ovarian cancer pathogenesis." (PMID 40076482, 2025). "Support for PPARγ playing a role in susceptibility to ovarian cancer in vivo comes from a study of mice heterozygous for PPARγ." (PMID 16131403, 2005). "CGZ and TGZ cause a decrease in ovarian cancer cell proliferation that is PPARγ independent." (PMID 21283708, 2011). "The expression of PPARγ/ABCG2 was correlated to chemoresistance in ovarian cancer clinical specimens as well." (PMID 40709184, 2025). "It was observed that bisphenol A-induced apelin expression in ovarian cancer cell lines activates cell proliferation via peroxisome proliferator-activated receptor gamma." (PMID 40076482, 2025). "ANGPTL4 is regulated by peroxisome proliferator-activated receptor γ (PPARγ), who has been observed to be significantly increased in malignant ovarian tumours (grade 1, 2 and 3) compared to benign and borderline tumours." (PMID 37388244, 2023). "ITGAV and ABCA5 have been reported to be associated with ovarian cancer and ADIPOQ and PPARG are associated with polycystic ovary syndrome." (PMID 35052428, 2021). "In ovarian cancer cells (i.e., Ovcar3, CaOv3, and Skov3 cells), PPARγ also directly regulates the transcription of miR-125b and silencing of miR-125 impaired the growth inhibitory capacity of PPARγ agonists." (PMID 28167956, 2017). "These ligands include ciglitazone, which inhibits cell growth by causing cell cycle arrest and apoptosis in ovarian cancer cells, and DIM-C-pPhtBu, which arrests the cell cycle by inducing PPARγ-dependent p21." (PMID 25734181, 2015). "Our observations suggest that in some cases the PPARγ network is stimulated to help ovarian cancer cells survive as suggested by Rosiglitazone treatment increasing the IC50s of MT19c and cisplatin." (PMID 21781307, 2011). "Collectively, our data indicates that PPAR(mRNA is present and is regulated by TZDs in ovarian cancer cells albeit to different degrees depending upon the cell type and the ligand used to activate PPARg." (PMID 21283708, 2011). "Previous studies suggested that the PPARγ agonist, Rosiglitazone, inhibited ovarian cancer cell growth and enhanced cisplatin therapy." (PMID 21781307, 2011). "To begin to understand the selective modulation of PPARγ by TZDs in ovarian cancer cells, we examined the mRNA and protein expression profiles of PPARγ and the activation of PPARγ's promoter following TZD treatment." (PMID 21283708, 2011). "The experiments described herein also demonstrate that the four TZDs have distinct actions on ovarian cancer cells possibly through both PPARγ dependent as well as independent pathways." (PMID 21283708, 2011). "Our findings also demonstrate that PPARγ agonists stimulate PPARγ expression, but to varying degrees in different ovarian cancer cells." (PMID 21283708, 2011). "We also identify a possible role for PPARγ and Rosiglitazone stimulation in mediating chemotherapy in some ovarian cancer cells." (PMID 21781307, 2011). "We investigated the effect of four TZDs—Rosiglitazone (Rosi), Ciglitazone (CGZ), Troglitazone (TGZ), and Pioglitazone (Pio)—on ovarian cancer cell proliferation, PPARγ expression and PPAR luciferase reporter activity." (PMID 21283708, 2011). "We have recently demonstrated that the cytoplasmic and nuclear expression of PPARγ increases progressively with the progression of ovarian carcinoma." (PMID 18349831, 2008). "In this study, we report the expression of PPARγ in different pathological grades and subtypes of ovarian carcinoma and discuss its possible function with the progression of the disease." (PMID 15583697, 2005).
ovarian carcinoma (continued). "The immunohistochemical expression of PPARγ during the progression of ovarian cancer can be related to the growth-promoting role of PPARγ previously shown in certain cancer." (PMID 15583697, 2005). "Significantly increased PPARγ immunoreactivity was observed in malignant ovarian tumours (grade 1, 2 and 3) compared to benign and borderline tumours (χ2=48.80, P<0.001)." (PMID 15583697, 2005). "The present result showed that COX-2 was induced by TNF-α in ovarian carcinoma cells and that TNF-α-induced COX-2 expression was suppressed by 15d-PGJ2, suggesting that COX-2 expression was under the control of PPARγ and NFκB pathway in the ovarian carcinoma." (PMID 15266333, 2004). "In addition to its dual effects on PPARγ upregulation and PGRMC1/2 expression pattern reversal, OA prevents ovarian cancer cells from migrating and causes them to undergo apoptosis." (PMID 39588118, 2024). "In addition, PPARγ can induce growth suppression of ovarian cancer by transcriptional upregulation of miR-125b and thereby inhibits proto-oncogene BCL3." (PMID 28881624, 2017). "In addition, recent studies have shown that ovarian cancer stem cells induce M2 polarization of macrophages by activating PPARγ and NF-κB." (PMID 27783989, 2016). "In this study we utilized molecular, physiological and pharmacological approaches to investigate the effect of the four different TZDs on ovarian cancer cells and determine whether these effects are PPARγ dependent or independent." (PMID 21283708, 2011). "In order to determine whether ovarian cancer cells express PPARγ, real time PCR and western blot analysis was performed." (PMID 21283708, 2011). "Neither vector changed the TZD-mediated cell proliferation suggesting this effect of TZDs on ovarian cancer cells may be PPARγ independent." (PMID 21283708, 2011). "When PPARγ is stimulated with Rosiglitazone, MT19c and cisplatin have significantly higher IC50s suggesting that PPARγ is promoting survival in at least some types of ovarian cancer cells, leading to poorer outcomes." (PMID 21781307, 2011). "Taken together, our results indicate that PPARγ may play a role in the onset and progression of ovarian cancer." (PMID 15583697, 2005). "Further research need to investigate the prognostic significance of PPARγ expression in ovarian carcinoma and whether therapeutic administration of ligands for this receptor may have clinical potential for the treatment of the disease." (PMID 15583697, 2005). "Taken together, these data strongly indicate that PPARγ may provide a protective effect against the development of chemically induced, as well as sporadic ovarian cancer." (PMID 16131403, 2005). "We also examined whether COX-2 expression was controlled through ligand-mediated activation of PPARγ in ovarian carcinoma cells." (PMID 15266333, 2004). "Furthermore, in cultured ovarian carcinoma cells, Western blot revealed that PPARγ and COX-2 expression was regulated conversely as a result of stimulation by 15-deoxy-Δ12, 14 PGJ2 (15-PGJ2), a PPARγ activator." (PMID 15266333, 2004). "In ovarian cancer, intensity and locationof PPARγ immunostainingwere examined in 28 carcinoma cases along with 28 normal, benign or borderline cases.Twenty six of 28 carcinomas showed strongly positive PPARγ stainingcompared to 2 weak-staining cases in the control group." (PMID 18784849, 2008). "However, it is still unclear whether COX-2 expression is controlled through PPARγ signalling in ovarian carcinoma cells." (PMID 15266333, 2004). "From these results, it was suggested that PPARγ activation might suppress COX-2 expression via the nuclear factor-κB pathway in the ovarian carcinoma cells and that low expression of PPARγ and high expression of COX-2 might be involved in carcinogenesis and progression of ovarian tumours." (PMID 15266333, 2004). "EPA-treated CaOV3 and SKOV3ip tumors showed increased PPARγ expression compared to the control, indicating its role in EPA-mediated ovarian cancer cell inhibition." (PMID 35326656, 2022).
ovarian carcinoma (continued). "We recently showed that LPA upregulates an oncogene ZIP4 in epithelial ovarian cancer (EOC) cells, mainly via PPARγ, and LPA’s cancer stem cell (CSC)-promoting activities are mediated by PPARγ." (PMID 31658655, 2019). "Thus, this PPARγ agonist proved to effectively inhibit the growth of an NB tumour xenograft, in keeping with similar findings obtained using PPARγ agonists against other types of tumour xenografts, such as colorectal, lung, prostate, bladder and ovarian cancer." (PMID 20068562, 2010). "Thus, the present results suggested that ligand-mediated PPARγ activation suppressed COX-2 expression via the NFκB pathway in the ovarian carcinoma cells, and that high expression of PPARγ and low expression of COX-2 might play an important role in inhibiting ovarian carcinogenesis." (PMID 15266333, 2004). "Therefore, in ovarian cancer’s lipid-rich microenvironment, M2 polarization is driven by PUFA metabolites, CD36/FABP4-mediated FA uptake, PPARγ activation, and cholesterol efflux via ABC transporters." (PMID 40709184, 2025). "Importantly, PPARG and ABCG2 expression colocalized in human tissues from chemoresistant ovarian cancer specimens, while the expression of both proteins was reduced in the chemosensitive ones." (PMID 41148824, 2025). "Overall, DHA has been investigated more in ovarian cancer, with many reports showing DHA inhibiting ovarian cancer in vitro and in vivo by modulating the oncogenic signaling of NFkB and MAPK pathways, PPARγ activation, ROS activation, and potentiating chemotherapy." (PMID 35326656, 2022). "In conclusion, the reciprocal correlation between COX-2 and PPARγ found in the present study implicates that COX-2 and PPARγ may contribute to ovarian carcinoma induction." (PMID 15266333, 2004). "Notably, the present extracellular flux analysis showed that the pharmacological inhibition of FABP4, FABP5, and PPARγ significantly ameliorated the reduced maximum respiration in ovarian carcinoma cell lines without affecting basal respiration." (PMID 40429934, 2025). "PPARγ is not the only PPAR isotype with differential expression observed in ovarian carcinomas." (PMID 16131403, 2005). "This discordance between the expression of PPARγ mRNA and protein after TZD treatment has not been observed nor examined previously, however, the levels of PPARγ protein after TZD treatment have been shown to be highly variable between ES-2 and PA-1 ovarian cancer cells." (PMID 21283708, 2011).